KDM5B (lysine demethylase 5B)
Diseases named in the same sentence as KDM5B in open-access papers (continued):
Sharing a sentence is not in itself a finding about the gene and the disease.
melanoma (continued). "Interestingly, several reports described a slow-cycling subpopulation of human melanoma cells that expressed high levels of KDM5B and could give rise to highly proliferative progeny with reduced KDM5B expression." (PMID 27974677, 2017). "Interestingly, the mitochondrial oxidative phenotype has been involved in the resistance to classical chemotherapy and BRAF inhibitors in the slow-cycling subpopulation of melanoma characterized by high expression of the lysine-specific demethylase 5B (KDM5B a.k.a." (PMID 24161908, 2013). "Slow-cycling melanoma persister cells are characterised by a high, reversible expression of H3K4 demethylase KDM5B." (PMID 35650266, 2022). "An independent study showed that SETDB1 cooperates with histone demethylase KDM5B/JARID1B to silence retroelements, which decreases antigen presentation in melanoma cells, efficiently promoting immune evasion." (PMID 35432344, 2022). "KDM5B-knockout melanoma cells treated with proteasome inhibitor MG132 significantly increased SETDB1 levels, suggesting a protective role for KDM5B in proteasome-dependent degradation of SETDB1." (PMID 36497341, 2022). "The scientific progress made in recent years in deciphering the cancer epigenome has revealed the critical roles of histone H3 lysine 4 (H3K4) JARID1B/KDM5B demethylase in the tumorigenesis of various human tumors, including melanoma." (PMID 34575678, 2021). "It has been shown that slow-cycling cells expressing the marker gene KDM5B (a histone H3K4 demethylase, also termed JARID1B) were involved in long-term melanoma growth." (PMID 34591417, 2021). "In line with the oncogenic roles of KDM5A and KDM5B, suppression of KDM5A or KDM5B delays tumor formation, metastasis, and drug resistance in breast, lung, melanoma, and gastric cancers." (PMID 30080846, 2018). "In melanoma, KDM5B (JARID1B) is regarded as a marker of slow-cycling melanoma cells which are essential for long-term tumor growth Our KDM5B (JARID1B) signature clearly reflects decreased gene activity in group 1 cells (Proliferation)." (PMID 27903987, 2017). "The influence of KDM5B in melanoma is not yet clear, as some studies suggest that KDM5B is associated with tumor cells and metastases, while others indicate that KDM5B acts as a tumor suppressor by regulating retinoblastoma proteins." (PMID 38004468, 2023). "In this regard, it has been demonstrated that slow-cycling melanoma cells intrinsically resistant to PLX4032, to many chemotherapeutic drugs and to radiotherapy, overexpressed KDM5B, the histone H3KA demethylase which contribute to maintain OXPHOS and to enhance GSH-related processes." (PMID 37534247, 2023). "Single-sorted melanoma cells can rapidly re-establish KDM5B heterogeneity irrespective of their initial KDM5B expression level." (PMID 35650266, 2022). "In congruence with reports on KDM5B-associated therapy persistence, we observed decreased drug susceptibility to MAPK signaling pathway inhibitor (MAPKi) treatment upon KDM5B upregulation irrespective of the melanoma cell line tested." (PMID 35650266, 2022). "To create an experimental model that allows the exogenous induction of KDM5B protein expression, we cloned a Tet-On 3G-system, in which KDM5B expression is driven by a doxycycline-inducible PTRE3G promoter and established stable melanoma cell clones (WM3734Tet3G-KDM5B and WM3734Tet3G-EGFP control)." (PMID 35650266, 2022). "Not surprisingly, KDM5B is overexpressed, and has been reported to play an oncogenic function, in a variety of cancers including breast cancer, melanoma, PCa, lung cancer, hepatocellular carcinoma, gastric cancer, neuroblastoma and leukemia." (PMID 33245716, 2020). "In accordance with this latter study, we could show that KDM5B is associated with non-proliferating cells, which is consistent with other previous studies where it was shown to be a marker for slow-cycling melanoma cells as well as involved in long-term melanoma growth." (PMID 27903987, 2017).
melanoma (continued). "JARID1B/RBP2–H1/KDM5B was found to be a transcriptional regulator with tumor-suppressive potential in melamoma cells and was used as a biomarker for a small subpopulation of slow-cycling melanoma cells." (PMID 23922798, 2013). "Interestingly, high KDM5B/JARID1B expression was previously reported in slow cycling therapy-resistant melanoma cells, and it is known that ZEB1 induces the upregulation of JARID1B in melanoma." (PMID 35432344, 2022). "KDM5B expression is significantly higher in tumors from non-responders to immune checkpoint blockade than in those from responders, and KDM5B inhibits anti-melanoma immunity by recruiting the H3K9 methyltransferase SETDB1 to suppress endogenous retroelements in a demethylase-independent fashion." (PMID 35805040, 2022). "On the contrary, the enhanced expression of KDM5B may be an early event in human melanoma progression compared with benign nevi and may not be associated with melanoma invasiveness, indicating that KDM5B might not be an appropriate choice as a prognostic marker." (PMID 27974677, 2017). "Nonetheless, 90 days of exposure of melanoma cells to BRAF inhibitors displays no multidrug resistance, leading to the elimination of IDTC markers such as NGFR and KDM5B and permanent resistance." (PMID 36224606, 2022). "However, despite the clear impact of KDM5B and SETDB1 on immune evasion, there have not been any studies on the effects of their inhibition in melanoma resistance to immunotherapies." (PMID 35515106, 2022). "KDM5A (JARID1A, RBP2) is a retinoblastoma RB-binding protein and mediates metastasis in estrogen receptor-negative breast cancers, while KDM5B (JARID1B or PLU-1) has roles in tumor maintenance, melanoma metastatic progression and resistance to cytotoxic agents and BRAF inhibitors." (PMID 28827149, 2017).
breast carcinoma (93 papers, 2007 to 2026). "In breast cancer and breast cancer cell lines, KDM5B shows copy number gain associated with increased transcript levels, especially in luminal breast cancer subtypes." (PMID 36697763, 2023). "Authors in this study also identified a mechanism for increased breast cancer invasion involving a KDM5B-metastasis-associated lung adenocarcinoma transcription (MALAT1)-hsa miR448 signalling axis." (PMID 28536364, 2017). "KDM5B was initially identified as a gene that was up-regulated by the tyrosine kinase HER2 in human breast cancer cells and its expression was shown to be closely associated with the malignant phenotype in breast cancer." (PMID 27974677, 2017). "Several of these genes have been previously linked to tumourigenesis in breast cancer, including KDM5B, RAD21, BIRC5, AURKA and MSRA." (PMID 27341628, 2016). "Treatment with both SID peptide and avermectins targets multiple key genes in the EMT pathway, including TGFB1, and it is noteworthy that inhibition of TGFβ activity has been associated with loss of KDM5B in basal-like breast cancer cells." (PMID 26460951, 2015). "Moreover, the KDM5B-NTT isoform is present in breast cancer cells and the TFAP2C-Myc-KDM5B complex is associated with the repression of p21, tumorigenesis, and therapeutic failure." (PMID 38004468, 2023). "Furthermore, KDM5B confers a transcriptomic heterogeneity in ER+ breast cancer, and high KDM5B expression increases the risk of therapeutic resistance." (PMID 35805040, 2022). "Higher KDM5B activity is associated with poor prognosis in patients with ER+ breast cancer." (PMID 35805040, 2022). "Interestingly, KDM5B is specifically expressed in breast luminal cells and its loss induces basal-type gene expression, suggesting that KDM5B is a luminal lineage-driving oncogene in breast cancer." (PMID 33245716, 2020). "Furthermore, it is interesting to note that two components of this pathway, namely ETS-1 and KDM5B, have themselves been implicated in breast cancer." (PMID 24582497, 2014). "Immunohistochemical assays and bioinformatic analysis of various cancer databases were performed to examine KDM5B expression levels in breast cancer." (PMID 41654562, 2026). "Across all breast cancer subtypes, KDM5B expression was marginally higher in the luminal subtype, followed by HER2 positive and triple negative." (PMID 40764352, 2025). "Overall survival (OS) in breast cancer patients with KDM5B mRNA expression was analyzed using the GEPIA database." (PMID 40764352, 2025). "In this regard, we conducted a detailed analysis to evaluate the repurposing potential of ABC by targeting the KDM5B oncogene in breast cancer." (PMID 40764352, 2025). "In vitro studies showed that ABC treatment reduced KDM5B expression in breast cancer cells and increased their sensitivity towards DOX treatment." (PMID 40764352, 2025). "Our findings highlight the repurposing potential of ABC, a well-established antiviral agent, as a novel therapeutic approach targeting the KDM5B oncogene in breast cancer." (PMID 40764352, 2025). "KDM5B gene expression was determined in breast cancer patient samples, and the cytotoxic activity and the effect of ABC sensitization on doxorubicin (DOX) were investigated in 2-D and 3-D cultures." (PMID 40764352, 2025). "Towards this, qPCR was performed on 53 breast cancer and 14 normal breast tissue samples to evaluate KDM5B expression." (PMID 40764352, 2025). "In vitro studies demonstrated that ABC treatment reduced KDM5B expression in breast cancer cells and increased their sensitivity towards DOX." (PMID 40764352, 2025). "The oncogenic significance of KDM5B in breast cancer was confirmed through the analysis of publicly accessible databases." (PMID 40764352, 2025). "The current study investigated the role of KDM5B in breast cancer and explored the repurposing potential of the antiviral drug abacavir (ABC)." (PMID 40764352, 2025).
breast carcinoma (continued). "Moreover, KDM5B and HDAC4 co-expression in differentiated mouse mammary glands and breast carcinomas indicates that their interaction may be associated with transcriptional repression of KDM5B under both physiological and pathological conditions in these tissues." (PMID 38769556, 2024). "In breast cancer cells, 70‐kDa heat‐shock protein and lysine demethylase 5B have been identified as proteins binding HMBA." (PMID 37984341, 2023). "We show here that one of these isoforms, namely KDM5B-NTT, accumulates in breast cancer cell lines due to remarkable protein stability relative to the canonical PLU-1 isoform, which shows a much faster turnover." (PMID 36697763, 2023). "For example, Lysine Demethylase 5B (KDM5B), a potentially novel E3 ligase is highly expressed in breast cancer at both transcriptomics and proteomics, and 98.8% (2448/2478) of cells expressing KDM5B are malignant cells in breast cancer." (PMID 37845222, 2023). "Due to the strong link between KDM5B and breast cancer, and the wealth of ChIP-seq datasets available in cell lines derived from this cancer type, we used KDM5B data from MCF-7 cells for these analyses." (PMID 36803422, 2023). "Studies have shown that the prognostic model genes TK1, LOX, KDM5B, PSMD4, and NFE2L3 are associated with breast cancer progression, prognosis stratification, and clinical drug resistance." (PMID 37767092, 2023). "In particular, the KDM5B-NTT isoform appeared to be relatively more highly expressed in MDA-MB-231 basal breast cancer cell lines than in MCF7 luminal breast cancer cell lines." (PMID 36697763, 2023). "In the MCF7 luminal estrogen-responsive breast cancer cell line, KDM5B is involved in the repression of several tumor suppressor genes, such as BRCA1 and CAV1." (PMID 36697763, 2023). "More recently, a KDM5B inhibitor, AS‐8351, has been demonstrated to inhibit the proliferation ability of breast cancer cell." (PMID 37220590, 2023). "KDM5B is related to tumors with worse prognoses, therapy resistance, inflammatory responses, metastasis development, and the proliferation of breast cancer cells through the repression of tumor suppressors, namely BRCA1, HOXA5, and CAV1." (PMID 38004468, 2023). "The histone demethylase KDM5B also acts as an oncogene in breast cancer cell proliferation and migration." (PMID 37394582, 2023). "Here, we showed that twelve different breast cancer lines express a truncated isoform in the N-terminal region, which we called KDM5B-NTT, containing exon-6, previously identified in another isoform." (PMID 36697763, 2023). "Generally, luminal breast cancers express higher levels of KDM5B, while triple-negative breast cancers express lower levels of KDM5B when compared to ER+ cancers." (PMID 38004468, 2023). "KDM5B knockdown pronouncedly inhibits estradiol (E2)-dependent tumor growth of ER+ breast cancer cells." (PMID 36509829, 2022). "KDM5B is frequently amplified and overexpressed in ER+ luminal breast cancer cells, and KDM5B governs the luminal lineage transcriptional program." (PMID 35805040, 2022). "Using single-cell RNA sequencing and Mass spectrometry, they confirmed higher KDM5B expression levels in luminal subtypes compared with basal-like breast cancer cells." (PMID 35800379, 2022). "ER+ primary tumour with higher KDM5B expression levels was more likely to develop local and distant metastatic recurrence in tamoxifen-treated breast cancer patients." (PMID 35800379, 2022). "KDM5A and KDM5B, which are commonly overexpressed in luminal breast cancer, modulate ER signaling, alter gene expression profiles, and promote endocrine therapy resistance." (PMID 35453496, 2022). "Recently, cumulative studies have shown that KDM5B is overexpressed in a variety of human cancers, including breast cancer, gastric cancer, lung cancer, and prostate cancer, demonstrating its oncogenic function." (PMID 35428764, 2022).
breast carcinoma (continued). "AS-8351, a new small molecule compound targeting KDM5B, has only been reported to inhibit tumor growth in breast cancer." (PMID 35428764, 2022). "For HDAC4 and other class IIa HDACs, some experimental evidence suggests a possible interaction with KDM5B in the context of breast cancer and other cell lines." (PMID 35899196, 2022). "For instance, KDM5B is overexpressed in a variety of cancer types, and high levels of KDM5B have been observed in breast cancer and PCa." (PMID 35454801, 2022). "An association of KDM5B/JARID1B, which encodes a histone H3 lysine 4 (H3K4) demethylase, with shorter disease-free survival was reported in breast cancer patients treated with endocrine therapy." (PMID 35800379, 2022). "Most of the patients with KDM5B gene mutation had a history of drinking, and most of the patients with KDM5C gene mutation had a family history of breast cancer, a history of chronic pancreatitis and a higher pancreatic cancer tumor grade." (PMID 35493099, 2022). "KDM5B has been reported to suppress STING expression in breast cancer cell lines, thus short-circuiting the cGAS–STING–TBK1–IRF3 signaling axis important for innate immunity." (PMID 32117236, 2020). "High expression of KDM5B in prostate and breast cancer cells supports a proliferative role of KDM5B16–18." (PMID 31776402, 2019). "KDM5B is overexpressed in breast cancer and thus likely inversely correlated with HEXIM1 expression." (PMID 31805991, 2019). "The regulation of breast cancer cell phenotype by KDM5B inhibitors was assessed using western blots, differentiation assays, proliferation assays, and a mouse model of breast cancer metastasis." (PMID 31805991, 2019). "Nevertheless, it was later observed that the deregulation of this protein is different among the different breast cancer subtypes, thus suggesting a crucial but ambivalent role for KDM5B depending on the cell type context." (PMID 31060229, 2019). "Upregulation of HEXIM1 expression levels plays an essential role in the inhibition of proliferation of breast cancer cells via KDM5B inhibitors." (PMID 31805991, 2019). "KDM5B is involved in regulation of luminal and basal cell specific gene expression in breast cancers." (PMID 31776402, 2019). "While an oncogenic role for KDM5B in the luminal subtype of breast cancer has been reported, there are also reports of tumor suppressor action of KDM5B." (PMID 31776402, 2019). "Our data also suggest that upregulation of HEXIM1 expression levels plays a critical role in the inhibition of proliferation, differentiation, and regulation of expression of major growth regulatory factors in breast cancer cells by KDM5B inhibitors." (PMID 31805991, 2019). "These miRNAs can decrease KDM5B protein expression in different breast cancer cell lines, including MCF-7 and at the same time increase their radio-sensitivity." (PMID 31060229, 2019). "Increased expression of KDM5B in TNBC cell lines and the luminal MCF7 cell line when compared to non-tumorigenic MCF10A and HBL100 is consistent with the reported increased expression of KDM5B in breast cancer relative to normal breast tissue." (PMID 31805991, 2019). "Although RS3195 seemed to consistently increase H3K4me3 levels both in yeast and in HeLa cells, it appears less effective in breast cancer cell line MCF-7 overexpressing KDM5B." (PMID 31060229, 2019). "Upregulation of HEXIM1 expression levels plays a critical role in the inhibition of proliferation of breast cancer cells using KDM5B inhibitors." (PMID 31805991, 2019). "Additional support for these datasets was provided by another study that demonstrated that CTCF can interact with the KDM5B histone demethylase and increase its demethylation activity in breast cancer cell lines." (PMID 29682202, 2018). "More recently, high KDM5B expression was found to correlate with poor prognosis in breast cancer patients and enhanced breast cancer invasiveness in triple negative breast cancers." (PMID 28536364, 2017).